DAB1 (DAB adaptor protein 1)
Diseases named in the same sentence as DAB1 in open-access papers (continued):
Sharing a sentence is not in itself a finding about the gene and the disease.
leukemia (2 papers, 2020 to 2023). A malignant (clonal) hematologic disorder, involving hematopoietic stem cells and characterized by the presence of primitive or atypical myeloid or lymphoid cells in the bone marrow and the blood. "The integration of ATAC‐Seq and RNA‐Seq data combined with an exon usage analysis thus revealed that the leukemias overexpress a previously unannotated isoform of DAB1 including additional exons." (PMID 32755029, 2020). "Dab1 expression reduced the proliferation of leukemia cells." (PMID 37491836, 2023). "Moreover, publicly available datasets generated with Affymetrix microarrays (U133) in larger patient cohorts demonstrated higher expression signal of DAB1 in leukemias, particularly in T‐ALLs (R2: Genomics Analysis and Visualization Platform)." (PMID 32755029, 2020). "Future work will be required to investigate whether this previously unrecognized transcript of DAB1 affects the viability or proliferation of leukemia cells in T‐ALL." (PMID 32755029, 2020). "We integrated ATAC‐Seq and RNA‐Seq and found DAB1, a gene not related to leukemia previously, to be overexpressed, abnormally spliced and hyper‐accessible in T‐ALLs." (PMID 32755029, 2020).
Leukoencephalopathy (2 papers, 2020 to 2021). This term describes abnormality of the white matter of the cerebrum resulting from damage to the myelin sheaths of nerve cells. "Three genes in the region: ORC1, SCP2, DAB1, may be candidates for the main phenotypes observed in our patient such as short stature, microcephaly, growth retardation, leukoencephalopathy and DD/ID." (PMID 33157955, 2020).
Tauopathies (2 papers, 2012 to 2023). "In summary, dab1 mutant mice provide an interesting model of human Tauopathies." (PMID 22355340, 2012).
-lymphoblastic leukemia (1 paper, 2021). "Dab1 overexpressed in T-lymphoblastic leukemia cells, however, misses exons 7 and 8 and might drive proliferation of these cells in a similar way." (PMID 33572344, 2021).
colon cancer (1 paper, 2024). "Inhibiting DAB1/Dab1, a gene activated by Notch signaling, reduces tumor invasion in colon cancer models." (PMID 38844562, 2024).
colorectal tumours (1 paper, 2018). "Through induction of DAB1 expression, Notch induces a DAB1/ABL/Rho GEF TRIO1 signalling cascade to promote invasive colorectal tumours." (PMID 29438985, 2018).
endometrial tumor (1 paper, 2011). "Similarly, decreased levels of Dab1 have been observed in brain and endometrial tumor tissue, as well as a variety of cancer cell lines." (PMID 22163036, 2011).
ganglioglioma (1 paper, 2011). A well differentiated, slow growing neuroepithelial neoplasm composed of neoplastic, mature ganglion cells and neoplastic glial cells. "For example, analysis of 29 gangliogliomas by real-time RT-PCR analysis revealed reduced levels of Dab1 RNA in tumors compared to normal brain tissue." (PMID 22163036, 2011).
melanoma (1 paper, 2021). A malignant, usually aggressive tumor composed of atypical, neoplastic melanocytes. "In summary, all patients affected with PDAC and melanoma in family 25-9-44 carried the DAB1, POLQ and FGFBP3 variants, whereas none of the healthy individuals carried all three variants." (PMID 34357098, 2021).
neuroblastoma (1 paper, 2011). Neuroblastoma (NB) is the most common solid, extracranial childhood tumor. "As Nova2 has previously been implicated in the exclusion of exons 9B and 9C in Dab1, we examined the expression of this splicing factor in neuroblastoma and retinoblastoma cell lines." (PMID 22163036, 2011). "As the Dab1 gene is located within an unstable region of the human genome and has been proposed to function as a tumor suppressor, we also investigate Dab1 expression and splicing in retinoblastoma and neuroblastoma cells." (PMID 22163036, 2011). "Analysis of Dab1 splice forms in retinoblastoma and neuroblastoma tumor cells revealed relative enrichment of Dab1-L-like (includes exons 7 and 8) and Dab1-E-like (excludes exons 7 and 8) transcripts in retinoblastoma and neuroblastoma, respectively." (PMID 22163036, 2011).
neuropathy (1 paper, 2022). A disorder affecting the nervous system that manifests with pain, tingling, numbness, and/or muscle weakness. "More recently, new causal-genes were identified in undiagnosed families, including PNKP in eight families with AOA4, MAG in one family with AOA and neuropathy, and DAB1 in three AD families with SCA37." (PMID 35326432, 2022).
pancreatic disease (1 paper, 2021). "A PCMS family carried pathogenic low-frequency variants in the DAB1, POLQ and FGFBP3 genes, with all three co-segregating with pancreatic disease." (PMID 34357098, 2021). "The present WGS, however, detected potentially pathogenic variants in the ATM, SUFU, DAB1, POLQ, MAP3K3, FGFBP3 and ACAD9 genes that co-segregated with pancreatic disease in single FPC families, and thus might predispose them to the disease." (PMID 34357098, 2021). "A new finding of the present study is that affected patients from one FPC family can carry identical germline variants in up to three different genes, e.g., DAB1, POLQ and FGFBP3 in family 25-9-44 or MAPK3 and ACAD9 in family 25-4-46, which segregate with pancreatic disease." (PMID 34357098, 2021).
periodontitis (1 paper, 2024). An acute or chronic inflammatory process that affects the tissues that surround and support the teeth. "The rs197620-A allele of DAB1 locus that associated with decreased abundance of order Actinomycetales, associated with higher risk of periodontitis." (PMID 38926497, 2024).
Polydipsia (1 paper, 2022). Excessive thirst manifested by excessive fluid intake. "Mice with Cx37 dab1−/− showed problems with body water handling via the kidneys, resulting in polyuria and polydipsia." (PMID 35327391, 2022).
prion disease (1 paper, 2025). A transmissible disease that is caused by a protein that is able to induce abnormal folding of normal cellular proteins, leading to characteristic spongiform brain changes, which are associated with neuronal loss without an inflammatory response. "The Reelin signaling pathway, implicated both in Alzheimer’s and prion diseases, engages Dab1, an adaptor protein influencing APP processing and amyloid beta deposition." (PMID 40733546, 2025). "This suggests a discrepancy between Reelin expression levels and Dab1 phosphorylation status, indicating potential dysfunction in the Reelin signaling pathway in the context of prion diseases." (PMID 40733546, 2025). "We showed that prion disease strongly impairs the Reelin signaling cascade, with a prominent reduction in Dab1 protein expression." (PMID 40733546, 2025). "Interestingly, reduced Dab1 expression is already pronounced in the pre-symptomatic stage of the infection, possibly suggesting that Reelin pathway disruption is an early event of prion diseases." (PMID 40733546, 2025). "Further research is necessary to fully elucidate the intricate relationship between Reelin expression, Dab1 phosphorylation, and disease pathology in neurodegenerative conditions like prion diseases, as the expression levels of Reelin alone are not considered to be diagnostic markers." (PMID 40733546, 2025). "Finally, as the role of the Reelin/Dab1 signaling cascade in prion diseases has not been deeply investigated, RML-inoculated mice were used as prion pathology models." (PMID 40733546, 2025). "Although the role of the Reelin signaling cascade in prion diseases has not been deeply investigated, it has been reported that APP processing and β-amyloid deposition in sporadic Creutzfeldt-Jakob disease (CJD) patients are dependent on Dab1." (PMID 40733546, 2025).
renal fibrosis (1 paper, 2021). A final common manifestation of a wide variety of chronic kidney diseases characterized by glomerulosclerosis and tubulointerstitial fibrosis. "Accordingly, we suggest that loss of Dab1 might lead to the activation of c-Src tyrosine kinase, resulting in the upregulation of Cx43 and subsequent attenuation of renal fibrosis and electric abnormalities by activation of the cyclic adenosine monophosphate (cAMP) pathway." (PMID 33525532, 2021). "One of the downstream targets of Dab1 is c-Src tyrosine kinase through which Cx43 was shown to diminish renal fibrosis." (PMID 33525532, 2021). "Additionally, we suggest that loss of Dab1 might lead to the activation of c-Src tyrosine kinase, resulting in the upregulation of Cx43 and subsequent attenuation of renal fibrosis and electric abnormalities by activation of the cyclic adenosine monophosphate (cAMP) pathway." (PMID 33525532, 2021).
renal hypoplasia (1 paper, 2025). Renal hypoplasia is a developmental anomaly in which one or both kidneys (unilateral or bilateral renal hypoplasia, respectively) have a deficit in the number of nephrons and may be small. "Our objective was to determine if these proteins engage with Reelin–Dab1 signaling to facilitate renal hypoplasia and influence the development of CAKUT." (PMID 40650197, 2025).
retinoblastoma (1 paper, 2011). A malignant tumor that originates in the nuclear layer of the retina. "Treatment of retinoblastoma cell line RB522A with Reelin resulted in increased tyrosine phosphorylation of Dab1." (PMID 22163036, 2011).
status epilepticus (1 paper, 2016). Status epilepticus is defined as a continuous seizure lasting more than 30 min, or two or more seizures without full recovery of consciousness between any of them. "Dab1-deficient mice did not have spontaneous seizures but exhibited interictal epileptiform abnormalities and a significantly reduced latency to pilocarpine-induced status epilepticus." (PMID 26941603, 2016).
vascular tumor (1 paper, 2024). "Significantly, the presence of vascular tumor invasion was associated with DAB1 gene methylation (No vs. Yes; OR = 0.274, 95% CI = 0.097–0.771) (p = 0.014)." (PMID 39199384, 2024).
cancer (11 papers, 2011 to 2024). A tumor composed of atypical neoplastic, often pleomorphic cells that invade other tissues. "The genomic alterations of PDGFRA, PARP1, CREBL2, and DAB1 cooperatively contributed to the abnormality of cancer hallmarks." (PMID 37491836, 2023). "Previous evidence has highlighted the significant involvement of DAB1 in cancer development." (PMID 38255219, 2024). "Notably, a reduction in DAB1 expression has been documented in primary tumors and various cancer cell lines, with a particular emphasis on brain and endometrial cancers." (PMID 38255219, 2024). "We asked whether a positive correlation between SMARCD3 and DAB1 exists in other human cancers or healthy organs." (PMID 36849558, 2023).
tumor (10 papers, 2011 to 2024). "The loss of DAB1 protein expression in the tumor tissue compared to healthy tissue suggests a somatic second hit." (PMID 34357098, 2021). "In addition, the immunohistochemistry of normal and PDAC tumor tissue revealed the normal expression of DAB1 in the gallbladder and plasma cells, but a loss of expression in the PDAC lesions, suggesting a somatic second hit in the tumor tissue." (PMID 34357098, 2021). "Then the ChIP-seq enrichment data from the four CREs proximal to the DAB1 locus in each tumour were pooled into either the higher or lower group." (PMID 36849558, 2023). "Collectively, these results indicate that MB hijacks SMARCD3–Reelin–DAB1-mediated cell migration, a neurodevelopmental programme in the cerebellum, to promote tumour metastatic dissemination." (PMID 36849558, 2023). "In this study we observed a higher expression of reelin and Dab1 transcripts in both peritumoral area and peritumoral-derived CSCs, with respect to the tumor core." (PMID 34205192, 2021). "Dab1 products were observed in all RB and NB tumor cell lines analysed, although there were significant variations in relative band intensities in the different cell lines." (PMID 22163036, 2011). "To investigate whether exogenous Reelin can induce Dab1 tyrosine phosphorylation in tumor cells, we treated RB522A cells with Reelin." (PMID 22163036, 2011). "We also report that Dab1 and Reelin are expressed in RB and NB cell lines suggesting that the Reelin-Dab1 signaling pathway may be active in these tumor cells." (PMID 22163036, 2011). "The human Dab1 gene is located within a common fragile site, and it has been postulated that it may function as a tumor suppressor." (PMID 22163036, 2011). "The possibility that Dab1 might function as a tumor repressor has been explored in a few studies." (PMID 22163036, 2011).
psychiatric disorder (4 papers, 2020 to 2024). A disorder characterized by behavioral and/or psychological abnormalities, often accompanied by physical symptoms. "DAB1, a key component of the Reelin pathway, is sufficient to induce behavioral deficits related to psychiatric disorders." (PMID 37029353, 2023). "In addition, Dab-1 conditional knockout mice exhibited hyperactive behaviors and impairment of working memory, which are symptoms observed in patients with psychiatric disorders." (PMID 39339187, 2024).
adenocarcinoma (2 papers, 2023 to 2024). A common cancer characterized by the presence of malignant glandular cells. "We have tested Pax5 motif in our cell lines and found that its target genes such as TNC or DAB1, which are highly expressed in NE-like cells, have increased promoter chromatin accessibility and histone acetylation compared to adenocarcinoma cells." (PMID 38168280, 2023).
infection (2 papers, 2025). The state of being infected such as from the introduction of a foreign agent such as serum, vaccine, antigenic substance or organism. "We adopted a GEE to examine the relationship between PCS and the occurrence of IgG against DAB1, AIFM1, and SURF1, comparing sera sampled approximately 12 weeks after infection from patients affected by PCS with patients with no long-term sequelae." (PMID 40995367, 2025).
neurodevelopmental disorder (2 papers, 2020 to 2023). A behavioral and cognitive disorder with onset during the developmental period that involves impaired or aberrant development of intellectual, motor, or social functions. "DAB1 is important for neurodevelopment and synaptic function, and has been associated with neurodevelopmental disorders." (PMID 33298905, 2020). "Their investigations revealed a mutation that can change the structure and stability of the protein coded by DAB1, potentially increasing susceptibility to neurodevelopmental disorders." (PMID 33298905, 2020).
neurological diseases (2 papers, 2016 to 2025). "The different connexin expression profile in yotari mice due to the Dab1 mutation suggests multiple avenues for investigation regarding neurodevelopment, vascular integrity, neuronal signalling, and potential relevance to human neurological diseases." (PMID 41463098, 2025).
kidney disease (1 paper, 2017). "Moreover, Ang II facilitated the reelin expression and Dab1 phosphorylation in vivo and in vitro, indicating that reelin and Dab1 were involved in kidney disease and podocyte injury." (PMID 28676854, 2017).
movement disorder (1 paper, 2021). Neurological conditions resulting in abnormal voluntary or involuntary movement, which may impact the speed, fluency, quality and ease of movement. "We suggested that DAB1 rs17115303 and PTPRT rs6030462 polymorphisms are genetic risk factors common to both diseases that directly or indirectly promote the accumulation of intraneuronal inclusions or neurodegeneration of DA and motor neurons, resulting in movement disorder." (PMID 34707478, 2021).
DAB1 also shares sentences with these, for which no sentence is quoted: Friedreich ataxia (3 papers); diabetes (2); epilepsy (2); Fuchs endothelial corneal dystrophy (2); gastric cancer (2); Obesity (2); adult familial myoclonic epilepsies (1); alcohol dependence (1); amyotrophic lateral sclerosis (1); Bladder Cancer (1); brain disorder (1); brain injury (1); CADASIL (1); Cerebellar hypoplasia (1); cervical cancer (1); choanal atresia (1); dentatorubral-pallidoluysian atrophy (1); development delay (1); diabetic nephropathy (1); dyslexia (1); essential tremor (1); frontotemporal dementia (1); glioma (1); hereditary disease (1); hyperlipidemia (1); hypothyroidism (1); intestinal cancer (1); Machado-Joseph disease (1); medulloblastoma (1); metastatic cancer (1).
A further 11 diseases each share a sentence with DAB1 in 1 paper.